LINC01145 (long intergenic non-protein coding RNA 1145 )
Gene: Long non-coding RNA gene on chromosome 1 (145,116,453 to 145,217,352, reverse strand). Ensembl gene ENSG00000290867.
Gene Ontology:
Molecular function: triplet codon-amino acid adaptor activity
Biological process: translation